DUOX2 (dual oxidase 2)
Diseases named in the same sentence as DUOX2 in open-access papers (continued):
Sharing a sentence is not in itself a finding about the gene and the disease.
Graves' hyperthyroidism (1 paper, 2023). "The genes related to the antithyroid effects of long-term iodine loading are Slc5a5, Slc26a4, Duox2, and Duoxa2, in addition to Tpo, Dio1, and Slco4a1, which are upregulated in Graves' hyperthyroidism." (PMID 36565031, 2023).
Hypoalbuminemia (1 paper, 2025). The concentration of albumin in the blood circulation is below the lower limit of normal. "In NEC, systemic inflammation and barrier dysfunction may underlie the coexistence of elevated DUOX2 expression and hypoalbuminemia." (PMID 41383848, 2025). "Our study demonstrated that DUOX2 levels were significantly elevated in NEC patients and independently associated with disease severity, showing correlations with RDW, LDH, and hypoalbuminemia." (PMID 41383848, 2025).
ischemia (1 paper, 2015). A hypoperfusion of the BLOOD through an organ or tissue caused by a PATHOLOGIC CONSTRICTION or obstruction of its BLOOD VESSELS, or an absence of BLOOD CIRCULATION. "Furthermore, statistical analysis revealed no significant decrease in the expression of SLC6A14 and DUOX2 in response to ischemia." (PMID 26222051, 2015).
Listeria monocytogenes infection (1 paper, 2021). "NOD2 in cooperative with DUOX2 protected against Listeria monocytogenes infection." (PMID 34299310, 2021).
lung disease (1 paper, 2006). "DUOX1 and DUOX2, which are expressed in lung epithelium, regulates H2O2 and acid production in the airway but have not been shown to be associated with lung disease." (PMID 16608528, 2006).
nematode infection (1 paper, 2018). "The role of PPARG, DUOX2 and IL5RA genes in relation to the immune response has been previously reported in different nematode infection studies." (PMID 29703268, 2018).
polyposis (1 paper, 2021). "We identified 3 missense variants in the DUOX2 gene (p.R683L, p.R1110Q, and p.L1343F) from 2 unrelated families with unexplained polyposis." (PMID 33628596, 2021). "There were 6 affected individuals in the 3 pedigrees with DUOX2-associated polyposis." (PMID 33628596, 2021). "Subsequently, using Sanger sequencing, we found other polyposis patients carrying variants of the DUOX2 gene, encoding dual oxidase 2, and analyzed them." (PMID 33628596, 2021). "Thus, it is necessary to include the DUOX2 gene in the genetic screening for adenomatous polyposis and to collect more patients with DUOX2-related polyposis in a larger population." (PMID 33628596, 2021). "Due to the small population size, we found only 3 DUOX2-related polyposis families." (PMID 33628596, 2021).
Protein-losing enteropathy (1 paper, 2025). Abnormal loss of protein from the digestive tract related to excessive leakage of plasma proteins into the lumen of the gastrointestinal tract. "While albumin decline likely reflects protein-losing enteropathy and enhanced catabolism, DUOX2 upregulation may exacerbate mucosal damage and inflammation, reinforcing a vicious cycle." (PMID 41383848, 2025).
pulmonary emphysema (1 paper, 2018). A subcategory of chronic obstructive pulmonary disease (COPD). "In conclusion, 2 × 106 BMMCs showed potent anti-inflammatory, antiapoptotic, antioxidant and restorative effects in papain-triggered pulmonary emphysema, possibly by blocking DUOX1 and reducing DUOX2." (PMID 29515461, 2018).
stomach adenocarcinoma (1 paper, 2021). "Our data confirmed that DUOX2 protein levels did not correlate with tumor type, grade or stages (data not shown), however we observed that more than 30% of human stomach adenocarcinoma are actually negative for DUOX2 while 21% show strong staining." (PMID 34439340, 2021). "This is particularly important since our IHC data indicate that over 30% of stomach adenocarcinoma (STAD) are negative for DUOX2 and an analysis of the TCGA database indicates that DUOX2 mRNA is not upregulated in STAD." (PMID 34439340, 2021). "This could be important in the event that such an approach reaches clinical applications, given that more than 30% of human stomach adenocarcinoma do not express DUOX2 at the protein level." (PMID 34439340, 2021).
thyrotoxicosis (1 paper, 2023). A hypermetabolic syndrome caused by the elevation of thyroid hormone levels in the serum. "It investigated the contribution of gene polymorphism to the development of type 2 amiodarone-induced thyrotoxicosis and showed that the risk of AIT2 is 3.18 times higher in the G/T of the DUOX2 gene carriers." (PMID 36835420, 2023).
transient congenital hypothyroidism (1 paper, 2023). A common, self-limiting thyroid disorder seen in preterm infants that is characterized by abnormally low serum levels of thyroxine and free thyroxine with normal serum levels of thyroid stimulating hormone. "These variants of carrier status were located in DUOX2 and DUOXA2 Genetic factors, in particular mutations in DUOX2 and DUOXA2 is a major contributor to the overall increase in the incidence of CH and transient congenital hypothyroidism (TCH)." (PMID 37147621, 2023).
viral infections (1 paper, 2022). "Out of seven NADPH oxidase homologs, four are implicated in ROS generation under viral infections: Nox1, Nox2, Nox4, and Duox2, but the primary source of inflammatory cell ROS is the Nox2 oxidase enzyme." (PMID 35281470, 2022). "Apart from Nox2, also Nox1, Nox 4, and Duox2 might play a role in the ROS formation of viral infections." (PMID 35281470, 2022).
tumor (34 papers, 2013 to 2025). "As a critical ROS-generating enzyme within the NOX family, dual oxidase 2 (DUOX2) has been implicated in tumor pathogenesis." (PMID 41154358, 2025). "Dual oxidase 2 (DUOX2) is a key glycoprotein that regulates cellular redox and is associated with chronic inflammation and tumor development." (PMID 39958351, 2025). "Microbial-dependent IL-17 signaling has been found to enhance DUOX2 signaling in tumor cells associated with pancreatic ductal adenocarcinoma." (PMID 39906741, 2024). "DUOX2 expression showed significant association with tumor diameter (P = 0.019) and TNM stage (P = 0.005), especially T and N stages (P = 0.041 and P = 0.001, respectively)." (PMID 33748270, 2021). "DUOX2 restoration fully reversed the tumor volume reduction caused by TCN1 knockdown." (PMID 41154358, 2025). "In the high DUOX2 expression group, the relative abundance of Escherichia coli, of which some strains are pathogenic, whereas others do not cause disease, along with Alistipes finegoldii, which has been associated with tumor formation, was increased." (PMID 37891968, 2023). "For example, modulation of DUOX2 expression could be by direct effect of drugs on tumors, mouse/human immune response to the tumor cells influenced directly or indirectly by drug exposure, and a response to tumor cell death caused by the drugs." (PMID 26719345, 2016). "IHC of tumor tissues mirrored these results, showing reduced DUOX2 staining in TCN1-knockdown tumors and elevated staining in TCN1-overexpressing tumors, indicating the transcriptional and translational regulation of DUOX2 by TCN1." (PMID 41154358, 2025). "In cancer, DUOX1 is frequently epigenetically silenced, consistent with tumor-suppressive roles, whereas DUOX2 is often upregulated and can promote tumor progression." (PMID 40867898, 2025). "Conversely, co-knockdown of DUOX2 in TCN1-overexpressing tumors significantly suppressed TCN1-driven tumor growth." (PMID 41154358, 2025). "Meanwhile, microbial-dependent IL-17 signaling increases DUOX2 signaling in tumor cells and promotes tumor development." (PMID 39906741, 2024). "The systemic spread of Th17 cells and B cells to distal organs facilitates tumor promotion via Dual oxidase 2 (DUOX2)." (PMID 39100682, 2024). "Alistipes finegoldii promotes tumor formation, and its high abundance in Duox2∆IEC mice is in agreement with the increased proliferation of DUOX2-deficient intestinal epithelial cells." (PMID 37891968, 2023). "Univariate analysis revealed that DUOX2 expression, tumor location, TNM stage, and N classification were considered as prognostic indicators for OS." (PMID 33748270, 2021). "On the other hand, the CI did span 1.0 for all tumor expressing reduced DUOX2 when compared to untreated samples." (PMID 34439340, 2021). "The results demonstrated that DUOX2 that is located in the cytoplasm showed an elevated expression in the tumor tissues when compared with adjacent normal samples." (PMID 33748270, 2021). "The NADPH oxidase family is one of the most relevant sources of ROS during cancer development NADPH oxidase 1 (NOX1) and Dual oxidase 2 (DUOX2) are examples of upregulated enzymes in tumor tissue." (PMID 33371444, 2020). "In univariate analysis, larger tumour size, with pharmaceutical drug adjuvant therapy, high FNCLCC grade, increased COL11A1, ITGA10 and KIF26B expression, and decreased CLEC3B, DUOX2, KRT75 and PPP2R2B were risk factors of shorter RFS." (PMID 31742892, 2020). "BxPC-3 cells treated with IFN-γ produced significantly more H2O2 over time compared to cells not incubated with IFN-γ (P < 0.001 at all times); and DPI treatment decreased DUOX2-mediated H2O2 release by the IFN-γ-stimulated tumor cells to near-basal levels." (PMID 27637085, 2016). "Most of the 13 surgically-resected PDAC samples we evaluated expressed DUOX2 at a higher level in tumor than in adjacent, resected uninvolved pancreas (P < 0.04 for the group as a whole)." (PMID 27637085, 2016).
tumor (continued). "These context-dependent effects suggest that the DUOX2-ROS may play a complex role in tumor resistance, with varying impacts depending on the type of tumor and treatment context." (PMID 40875107, 2025). "However, the relationship between ROS production mediated by DUOX2 and tumor resistance remains elusive." (PMID 40875107, 2025). "Collectively, the data point to a functional connection among TCN1, STAT4, and the DUOX2/ROS axis that, by modulating oxidative stress, may constitute a tumor cell–autonomous oncogenic route in PDAC." (PMID 41154358, 2025). "In addition, dual oxidase 2 (DUOX2), a gene whose expression is differentially modulated by IL‐17A, was primarily detected in tumor cell clusters derived from mice with IL‐17RA deficiency." (PMID 38585232, 2024). "Because an increase in angiogenesis could sensitize cancer cells to radiation through tissue reoxygenation, we then measured the effect of our regimen on angiogenesis factors in tumor expressing endogenous or reduced DUOX2 levels." (PMID 34439340, 2021). "We performed RNA sequencing for 30 pairs of TNBC tissue and matched normal tissue from our hospital, and identified five pivotal genes (GALNTL5, MLIP, HMCN2, LRRN4CL, and DUOX2), which were correlated with associated with CD8+ T cell infiltration, tumor progression and therapeutic efficacy." (PMID 35046993, 2021). "Furthermore, our study disclosed that tumor diameter, T stage, and N stage were in relation to DUOX2 expression." (PMID 33748270, 2021). "The capacity to upregulate DUOX2 at the protein level in a particular tumor could thus serve as a potential valuable biomarker for chemopotentiation by LD-WART." (PMID 34439340, 2021). "Furthermore, the CRC tissue had more DUOX2 protein than the control tissue, especially at the circumference of tumor." (PMID 26839536, 2016). "Both facts might explain the observation that qPCR results only revealed trends, not significant changes, in the expression levels of DUSP1, CYR61, SLC6A14 and DUOX2 in tumor ischemic colorectal tissue samples." (PMID 26222051, 2015). "We found, furthermore, that following heat-denaturation of our tumor cell lysates, Duox2 protein appeared to aggregate as a high molecular weight band, whereas Duox2 protein was recognized at the expected, ∼185 kDa size in non-heat denatured samples from the overexpressing cell line." (PMID 23404210, 2013). "Because no reliable Duox antibodies are commercially available, we report the development of a murine monoclonal antibody (MAb) to Duox2 (clone Duox S-12) and its use for the characterization of Duox2 expression in human tumors, tumor cell lines and normal tissues." (PMID 23404210, 2013). "In addition, the higher gene expression level of DUOX2 in tumor samples with elevated levels of RP11-109D20.2 lncRNA may suggest a potential link between these genes." (PMID 40666182, 2025). "Moreover, Duox2 has been identified as a contributor to establishing a pro-angiogenic extracellular environment, which may further promote tumor growth and leukocyte infiltration." (PMID 40909948, 2025). "However, overexpression of DUOX2 may lead to excessive ROS production, which can promote tumor progression." (PMID 26839536, 2016). "Hence, we chose to develop a Duox2 monoclonal antibody that would be applicable to a variety of investigative applications in clinical specimens so that a full characterization of Duox2 expression in normal as well tumor tissues would be possible." (PMID 23404210, 2013). "After AOM and DSS administration, there was less CTS in Duox2 CKO mice than WT littermates evidenced by significant lower number, size, and tumor load of macroscopic polyps (p < .05)." (PMID 38659246, 2024). "Cox regression analysis includes the following parameters: gender, age, tumor diameter, tumor location, TNM stage, T stage, N stage, histological stage, serum CA-199, serum CEA, perineural invasion, and DUOX2 mRNA." (PMID 33748270, 2021).
tumor (continued). "DTC metastatic tumor cells, in comparison with primary tumor cells, experience a considerable reduction in the amount of essential genes necessary for RAI, such as TG, TSH-R, and Duox2, but a relatively low reduction of NIS and TPO genes." (PMID 33673669, 2021). "Our current experiments were performed to examine the consequences of cytokine-mediated DUOX2 up-regulation (and concomitant enhancement of H2O2 formation) on downstream effectors of malignant transformation and tumor progression." (PMID 27637085, 2016). "When paraffin-embedded, Duox2-overexpressing MIA PaCa-2 cell pellets were examined with our Duox S-12 antibody, we found the expected, prominent immuno-staining of the tumor cell plasma membrane." (PMID 23404210, 2013). "Thus, we felt that it was reasonable to examine human tumor tissue microarrays for expression of Duox protein with our Duox S-12 antibody under the operating assumption that we would, for the most part, be evaluating the expression and distribution of Duox2 in such experiments." (PMID 23404210, 2013). "Conversely, TCN1 overexpression upregulated DUOX2 expression and promoted EMT, and this effect was abolished by STAT4 knockdown, indicating that TCN1 regulates DUOX2 through STAT4 to drive EMT-mediated tumor aggressiveness." (PMID 41154358, 2025). "Furthermore, heatmap analysis revealed that TREX1 and RRM2 expression levels were significantly higher in tumor tissues compared to normal tissues, whereas GPX2, DUOX1, and DUOX2 were expressed at lower levels in tumor tissues." (PMID 41346575, 2025). "Moreover, in non-tumor hepatocyte, such as HepaRG cells, NOX1 and NOX4 are even lower (at least by an order of magnitude); however, in these, DUOX2 is readily detected." (PMID 37189460, 2023). "Nonetheless, the CI did not span 1.0 for tumor expressing endogenous DUOX2 levels exposed to LD-WART alone or combined with chemotherapy when compared to the untreated control." (PMID 34439340, 2021). "PL restored ROS level (mainly via reversing Duox2/Gpx2), activated oxidative stress/inflammation/immune responses signature genes, reduced cancer cell proliferation/invasion, increased apoptosis and CD3+/CD4+/CD8+ T-lymphocytes in G422TN-tumor on the basis of RT/TMZ regimen." (PMID 37161450, 2023). "In pathological angiogenesis, DUOX2-induced ROS generation could activate proteins, such as serine/threonine kinase (AKT) and signal transducer and activator of transcription 3 (STAT3), which are known to promote tumor angiogenesis." (PMID 37891879, 2023). "Therefore, although decreased, the expression of TSH-R, NIS, pendrin, TPO and TG is preserved, while the expression of Duox2 is not altered or is slightly increased, and these tumor cells can even synthesize TH." (PMID 33673669, 2021). "In IFN-γ-stimulated tumor cells exposed to a DUOX2-specific siRNA, however, in addition to a lack of DUOX2 expression and decreased HIF-1α expression, we observed diminished ERK and S6 activation (compare lane 4 to lane 2) as well as no phosphorylation of 4E-BP1." (PMID 27637085, 2016). "The increased levels of angiogenesis could thus have contributed to increased HIF-1 basal levels in the DUOX2 negative tumors and increased drug uptake in both tumor types, especially since cisplatin can be retained in red blood cells for up to two years after treatment." (PMID 34439340, 2021). "Not just limited to tumor cells, we see that MEF Nf2−/− cells support elevated levels of NOX4 and DUOX2 compared to MEF Nf2fl/fl." (PMID 33410252, 2021). "As in non-metastatic tumor thyroid tissue, the efficacy of radioiodine therapy will depend mainly on the presence of NIS to accumulate iodine and on the TPO/Duox2 system to oxidize radio-iodide into TG radioiodine." (PMID 33673669, 2021).
tumor (continued). "In DTC, an increase in ROS is observed, mainly as a result of Duox2 (not because the expression of Duox2 increases, but by decreasing the expression of TPO, the production of H2O2 generated by Duox2 is not consumed and accumulates in the tumor cell)." (PMID 33673669, 2021). "Furthermore, qPCR results confirmed the microarray expression data of RGS1 and EEF1A1 in tumor ischemic colorectal tissue samples whereas differential expression of DUSP1, CYR61, SLC6A14 and DUOX2 in tumor ischemic colorectal tissue samples could not be validated." (PMID 26222051, 2015).